SCNN1A (sodium channel epithelial 1 subunit alpha)
Diseases named in the same sentence as SCNN1A in open-access papers:
SCNN1A is named in the same sentence as 71 diseases in open-access papers, as found by Europe PMC text mining. Sharing a sentence is not in itself a finding about the gene and the disease. The quoted sentences say what the papers report.
breast carcinoma (16 papers, 2008 to 2025). "Current studies on ENaC in cancer have shown that in breast cancer and neuroblastoma, SCNN1A gene silencing caused by hypermethylation in the promoter region of the SCNN1A gene, which encodes the α subunit of ENaC, is the main reason for the poor prognosis of patients with these tumors and diseases." (PMID 37359529, 2023). "Gene expression data from the microarray analysis of 92 primary breast tumors (from the UNC Microarray Database) were analyzed for expression of the six genes (CEACAM6, CDH1, CST6, ESR1, LCN2, and SCNN1A) whose loss characterizes the hypermethylator phenotype among breast cancer cell lines." (PMID 18221536, 2008). "In addition, an RNA sequence analysis showed that the breast cancer-associated fusion transcript SCNN1A-TNFRSF1A may play a role in the development of breast cancer." (PMID 31146704, 2019). "Studies have also reported the hypermethylation of the SCNN1A promoter and the subsequent silencing of expression in neuroblastoma and breast cancer with poor prognoses." (PMID 40136342, 2025). "The correlation between SCNN1A expression in breast cancer patients and migration gene profile was examined in the SCAN-B data-set." (PMID 40220219, 2025). "In breast cancer, a study has shown the potential biomarker of recurrent readthrough fusion transcripts of SCNN1A-TNFRSF1A (TNF receptor superfamily member 1A) as targets for anticancer treatment." (PMID 36139696, 2022). "SCNN1A is an ion transport gene that has been reported to be one of six genes that contribute to a hypermethylator phenotype that is seen in a subset of breast cancer cell lines and primary tumors." (PMID 21314941, 2011). "As mentioned in the previous section, it has been substantiated that the proliferation of breast cancer cells harboring the two conjoined genes, SCNN1A-TNFRSF1A and CTSD-IFITM10, could be decreased by targeting them with the corresponding siRNAs." (PMID 29414922, 2018). "ANGPTL4, PIEZO2, SCNN1A, LTBP1, and SerpinB2 promote the survival of breast cancer cells in the brain microenvironment." (PMID 37108248, 2023). "CDH1, CST6, MUC1 and SCNN1A genes, all reported to be aberrantly hypermethylated in breast cancer, were down-regulated in both MDA-MB-231 and Hs578T GLO1-depleted breast cancer cells when compared with control." (PMID 36998085, 2023).
ovarian carcinoma (6 papers, 2021 to 2025). A malignant neoplasm originating from the surface ovarian epithelium. "A separate investigation has provided evidence that SCNN1A is associated with unfavorable clinical outcomes in individuals afflicted with ovarian cancer, and exerts an impact on the immune cell infiltration patterns within the tumor microenvironment." (PMID 37251077, 2023). "In ovarian cancer, SCNN1A expression is associated with patient prognosis." (PMID 41465326, 2025). "Specifically, high expression of SCNN1A is associated with poorer overall survival and PFS in ovarian cancer patients." (PMID 41465326, 2025). "Studies have shown that SCNN1A is overexpressed in ovarian cancer and promotes cell proliferation, migration and predicts poor prognosis by regulating epithelial-mesenchymal transition." (PMID 36713456, 2022). "Overexpression of SCNN1A was found in ovarian cancer tissues and cell lines, and higher expression was related to poor survival." (PMID 36139696, 2022). "This suggests SCNN1A could be a potential biomarker for prognosis in ovarian cancer." (PMID 41465326, 2025).
arterial hypertension (4 papers, 2018 to 2023). "Liddle syndrome is genetic autosomal dominant form of low renin arterial hypertension caused by germline mutations in the SCNN1A, SCNN1B and SCNN1G genes, encoding, respectively, the α, β and γ subunits of the epithelial sodium channel ENaC." (PMID 29534496, 2018). "Hypermethylation of SCNN1A at CpG islands within the transcriptional region was associated with increased risk of developing hypertension." (PMID 29649151, 2018). "Hypermethylation of CpG islands within exons is typical of expressed genes, suggesting that SCNN1A gene is highly expressed in hypertension." (PMID 29649151, 2018).
neuroblastoma (4 papers, 2011 to 2025). Neuroblastoma (NB) is the most common solid, extracranial childhood tumor. "In our study, a low methylation frequency of SCNN1A, PRKCDBP and KRT19 is significantly associated with favorable outcome in neuroblastoma." (PMID 21314941, 2011). "We present eight genes (KRT19, PRKCDBP, SCNN1A, POU2F2, TGFBI, COL1A2, DHRS3 and DUSP23) that are methylated in neuroblastoma, most of them not previously reported as such, some of which also distinguish between biological subsets of neuroblastoma tumors." (PMID 21314941, 2011).
pseudohypoaldosteronism type 1 (4 papers, 2013 to 2021). A rare, primary form of mineralocorticoid resistance characterized by mild to profound salt wasting either restricted to the kidney (renal pseudohypoaldosteronism type 1), or generalized affecting many organs (generalized pseudohypoaldosteronism type 1). "Furthermore, some genes may be completely lacking in the zebrafish, such as the ENaC (epithelial Na channel) subunits (SCNN1A, SCNN1B, SCNN1G, and SCNN1D), mutations in which cause Liddle syndrome and pseudohypoaldosteronism type 1 in humans." (PMID 30200518, 2018).
bronchiectasis (3 papers, 2020 to 2023). Segmental, irreversible dilation of the bronchial tree resulting in the accumulation of secretions which leads to obstruction. "In addition, SAE ionocytes also expressed the high levels of epithelial Na+ channel genes (SCNN1A, SCNN1B, SCNN1G), risk genes relevant to CF and bronchiectasis." (PMID 32727470, 2020).
Liddle syndrome (3 papers, 2018 to 2019). A rare genetic form of low-renin hypertension characterized by hypertension associated with decreased plasma levels of potassium and aldosterone. "Liddle syndrome is associated with germline mutations in an allele of SCNN1A, SCNN1B or SCNN1G genes." (PMID 31655555, 2019). "The cause of Liddle syndrome is missense or frameshift mutations in SCNN1A, SCNN1B, or SCNN1G genes that encode epithelial sodium channel subunits." (PMID 31655555, 2019). "The molecular basis of Liddle syndrome resides in germline mutations of the SCNN1A, SCNN1B and SCNN1G genes, encoding the α, β, and γ-subunits of the epithelial Na+ channel (ENaC), respectively." (PMID 29534496, 2018). "Liddle syndrome results from germline mutations in SCNN1A, SCNN1B or SCNN1G genes." (PMID 29534496, 2018). "The diagnosis of Liddle syndrome is based on SCNN1A, SCNN1B and SCNN1G gene sequencing." (PMID 29534496, 2018).
pancreatic cancer (3 papers, 2022 to 2024). "SCNN1A promotes ovarian and pancreatic cancer cell proliferation and migration and inhibits osteosarcoma growth." (PMID 36915125, 2023). "Interestingly, a recent study explored the role of homology cassette D9 (HOXD9) and sodium channel epithelial cell 1α subunit (SCNN1A) in pancreatic cancer (PC) progression." (PMID 39511608, 2024). "Another study showed that SCNN1A upregulation by homeobox D9 (HOXD9) induced cell proliferation and migration in pancreatic cancer cells." (PMID 36139696, 2022).
melanoma (2 papers, 2019 to 2021). A malignant, usually aggressive tumor composed of atypical, neoplastic melanocytes. "Such five genes (namely, SCNN1A, GJB3, KCNK7, GJB1, KCNN2) are novel potential melanoma markers or molecular targets, never previously related to melanoma." (PMID 30934896, 2019). "Five such genes (namely: SCNN1A, GJB3, KCNK7, GJB1, KCNN2) were identified as potential strong melanoma markers that had never been identified before." (PMID 30934896, 2019).
preeclampsia (2 papers, 2013 to 2025). Preeclampsia is a hypertensive disorder of pregnancy that is characterized by new-onset hypertension with proteinuria presenting after 20 weeks of gestation, and depending on mild or severe forms may initially present with severe headache, visual disturbances, and hyperreflexia. "Renal gene expression of Hsd11b2, Sgk1, Scnn1a, Nox4, and Fn1 was not different between mice who had a normal pregnancy and mice who had a preeclampsia-like pregnancy at 5 or 10 weeks postpartum (respectively)." (PMID 40425613, 2025).
viral infection (2 papers, 2010 to 2017). "Finally, both PDE2A (MIM 602658) and SCNN1A (MIM 600228) might play a role in maintaining lung epithelial barrier homoeostasis during viral infection." (PMID 20174570, 2010).
autoimmune hepatitis (1 paper, 2025). Hepatitis caused by autoantibodies. "We report a unique clinical presentation involving a patient who was diagnosed at the age of 1 month with PHA type 1 caused by a mutation of SCNN1A and who was diagnosed with autoimmune hepatitis." (PMID 40303555, 2025). "The infant was later diagnosed with PHA type 1 caused by a mutation of SCNN1A, and she had persistent elevation of liver enzymes, for which she was diagnosed with autoimmune hepatitis." (PMID 40303555, 2025).
bipolar disorder (1 paper, 2011). A disorder of the brain that causes unusual shifts in mood, energy, activity levels and the ability to carry out day-to-day tasks. "For example, the ubiquitous protein, UBC, was abnormally expressed in schizophrenia samples and interacted with the maker genes of schizophrenia (i.e. TSC2, SCNN1A and USP2), bipolar disorder (i.e. MUSK), and major depression (i.e. MUSK and FLT3)." (PMID 22373040, 2011).
chronic obstructive pulmonary disease (1 paper, 2023). A chronic and progressive lung disorder characterized by the loss of elasticity of the bronchial tree and the air sacs, destruction of the air sacs wall, thickening of the bronchial wall, and mucous accumulation in the bronchial tree. "An ASO targeting the Scnn1a mRNA that encodes a subunit of the ENaC sodium channel has been tested in cystic fibrosis patients and may also have benefits in other lung diseases characterized by mucus dehydration such as chronic obstructive pulmonary disease (COPD)." (PMID 36727438, 2023).
Hyponatremia (1 paper, 2024). An abnormally decreased sodium concentration in the blood. "Additionally, we see downregulation of ENaC subunits (SCNN1A,B,D,G), a phenomenon that is associated with hyponatremia and metastasis in ccRCC." (PMID 39038934, 2024).
in situ carcinoma (1 paper, 2025). A malignant epithelial neoplasm which is confined to the epithelial layer without evidence of further tissue invasion. "Subsequent qPCR and IHC findings confirmed that SCNN1A and EFNA1 were highly expressed in both in situ carcinoma and OV-derived exosomes, supporting their potential as reliable biomarkers for OV." (PMID 40787466, 2025).
metastatic melanoma (1 paper, 2021). A melanoma that has spread from its primary site to another anatomic site. "Even more decrease of the ACCN3, SCNN1A, and SCNN1G expression was observed in comparison of primary malignancies and metastatic melanoma samples." (PMID 34680442, 2021).
neuroendocrine carcinoma (1 paper, 2022). A malignant neuroendocrine neoplasm composed of cells containing secretory granules that stain positive for NSE and chromogranin. "SCNN1A has been reported to be the direct transcriptional target of the oncogene achaete-scute homolog 1, which can be pharmacologically targeted with antitumor effects in neuroendocrine cancer cells." (PMID 36139696, 2022).
Parkinson disease (1 paper, 2020). A progressive degenerative disorder of the central nervous system characterized by loss of dopamine producing neurons in the substantia nigra and the presence of Lewy bodies in the substantia nigra and locus coeruleus. "We evaluated the recent literature on candidate blood biomarkers in Parkinson’s disease patients and observed five differentially methylated genes (COL9A2, SCNN1A, AMICA1, SLC16A3, and DLK1) in these studies within our conserved human regions." (PMID 32178731, 2020).
Pleural effusion (1 paper, 2025). The presence of an excessive amount of fluid in the pleural cavity. "Reclustering and cytoTRACE-based assessments of pleural effusion-derived metastases again revealed a positive correlation between the expression of EFNA1 and SCNN1A and the differentiation potential." (PMID 40787466, 2025).
seminoma (1 paper, 2022). A radiosensitive malignant germ cell tumor found in the testis (especially undescended), and extragonadal sites (anterior mediastinum and pineal gland). "We observed a significant decrease in the expression of SCNN1A in seminoma, probably due to the occurrence of PTC in downstream exons caused by AS in exon 3, which ultimately affected the levels of its mRNA transcripts." (PMID 36713456, 2022).
cancer (13 papers, 2013 to 2025). A tumor composed of atypical neoplastic, often pleomorphic cells that invade other tissues. "SCNN1A, which encodes the α-subunit of the epithelial sodium channel, is aberrantly expressed in OV, pancreatic, and other cancers." (PMID 40787466, 2025). "SCNN1A encodes the α subunit of epithelial sodium channel and was reported to be relevant to tumor progression in a variety of cancers." (PMID 37251404, 2023). "Further studies of the SCLC cell line H889 found that the SCNN1A gene encoding the α-subunit of ENaC directly correlates with the expression of ASCL1, which is essential in cancer cell progression and survival, for example, in a subset of lung cancer." (PMID 37408210, 2023). "The CNV gain in the 43 kb region in 12p13.31 in 601covers the genes SCNN1A, LTBR and CD27 and CD27 overexpression has been found to be associated with the development of different cancers." (PMID 30975103, 2019). "Among other genes in the modules, SH2D3A, AP1M2, CDS1 and SCNN1A haven’t been previously studied in cancer biology." (PMID 28651527, 2017). "Collectively, SCNN1A may play a role in proliferation and migration in cancers." (PMID 36139696, 2022). "Recent studies have elucidated the biological roles of SCNN1A and EFNA1 in cancer." (PMID 40787466, 2025). "HOXD9 has been shown to promote cancer development via transcriptional activation of oncogenes, such as RUN and FYVE domain containing 3 (RUFY3), Snail family transcriptional repressor 1 (SNAI1), Sodium channel epithelial 1α subunit (SCNN1A) and Hemicentin 1 (HMCN1)." (PMID 36907878, 2023). "The cell lines expressed one constitutively active Na+ channel (SCNN1A) and one voltage-gated Na+ channel (SCN3A) as well as about 200 voltage-gated K and Ca2+ channels with no major differences in the number or level of expressed ion channel genes between carcinoma cells and normal cells." (PMID 23505537, 2013).
tumor (11 papers, 2010 to 2025). "Tumor cells exhibited significant enrichment of exosome-associated genes, most notably SCNN1A and EFNA1, which were significantly upregulated in metastatic lesions and correlated with a poorer prognosis." (PMID 40787466, 2025). "Furthermore, SCNN1A-mediated sodium transport may alter extracellular matrix composition and intercellular interactions, further exacerbating tumor aggressiveness and the risk of distant metastasis." (PMID 40787466, 2025). "Previous studies have revealed the correlation of SCNN1A with tumor progression." (PMID 36139696, 2022). "In summary, we detected six DEGs (RIPK4, SCNN1A, SLC4A11, ELF3, CLDN4, and SOBP) which can serve as tumor markers for the diagnosis and prognosis of OC." (PMID 33742531, 2021). "In a study recently published, basal-like tumour cell lines were characterized by the concomitant hypermethylation of a six gene panel (CDH1, CEACAM6, CST6, ESR1, LCN2, SCNN1A)." (PMID 20338046, 2010). "Moreover, functional assays confirmed that SCNN1A and EFNA1 are highly expressed in well-differentiated tumor cell subpopulations and contribute to tumor progression by modulating cell migration, invasion, and immune evasion." (PMID 40787466, 2025). "IHC analysis demonstrated a progressive increase in SCNN1A and EFNA1 expression from adjacent non-tumor tissue to primary tumors and metastatic foci, with notably higher levels in subpopulations of tumor cells exhibiting a higher differentiation capacity." (PMID 40787466, 2025).
SCNN1A also shares sentences with these, for which no sentence is quoted: hypertension (3 papers); infection (3); abortion (2); adenocarcinoma (2); diabetes (2); Miscarriage (2); pneumonia (2); Ureteral obstruction (2); acute respiratory distress syndrome (1); Arrhythmia (1); atherosclerosis (1); autosomal recessive pseudohypoaldosteronism type 1 (1); breast tumors (1); bronchitis (1); cardiomyopathy (1); chronic kidney disease (1); colitis (1); COVID-19 (1); cystic fibrosis (1); cystic kidneys (1); edema (1); emphysema (1); endothelial dysfunction (1); essential hypertension (1); glaucoma (1); glioblastoma (1); glioma (1); gynecological cancers (1); hepatocellular carcinoma (1); lung adenocarcinoma (1).
A further 18 diseases each share a sentence with SCNN1A in 1 paper.